RB1 (RB transcriptional corepressor 1)
Diseases named in the same sentence as RB1 in open-access papers (continued):
Sharing a sentence is not in itself a finding about the gene and the disease.
breast cancer (continued). "In order to validate the readthrough ability of G418 for this RB1 nonsense mutant, we transiently transfected the RB1-negative breast carcinoma cell line MDA-MB-436 with a construct containing the complete RB1 R579X nonsense mutant cDNA with an N-terminal FLAG tag (see R579X)." (PMID 37917619, 2023). "Additionally, loss-of-function alterations in RB1, predicted to contribute to CDK4/6 inhibitor resistance, were observed in 13.3% (6/56) of CDK4/6 inhibitor-treated HR+ HER2- breast cancer patients." (PMID 35486650, 2022). "Bioinformatics analyses reveal that LPAR6 acts as a tumor suppressor in breast cancer and may inhibit tumor progression by facilitating the formation of RB1/E2F family complexes to induce cell cycle arrest." (PMID 34510318, 2022). "In line with studies in breast cancer, RB1 knockout reduced sensitivity to palbociclib." (PMID 35197447, 2022). "Estrogen might exert its physiological functions through lncRNAs, such as ERINA, an estrogen-responsive lncRNA, which promotes breast cancer development through the E2F1/RB1 pathway." (PMID 35685427, 2022). "Interestingly, RB1 exon deletions are seen not only in RB but also less frequently in breast cancer, osteosarcoma and lung cancer." (PMID 34294096, 2021). "In addition, CDK4/6i treatment led to RB1 protein reduction in a time-dependent manner in multiple breast cancer cell lines." (PMID 34508104, 2021). "As mentioned in the Introduction, it has been suggested that RB1 expression in TNBC might be used as a biomarker for the inhibitory effect of GLUT1 inhibitors on breast cancer." (PMID 34525987, 2021). "Notably, in keeping with previous reports, we found that CDK6 silencing was the top scoring genetic event for enhancing efficacy of CDK4/6i, and RB1 depletion was the top hit for promoting resistance in breast cancer cells to CDK4/6i." (PMID 34508104, 2021). "Similarly, RB1 inactivation in breast cancers enhances stem cell-like behaviors and malignant progression through IL-6 and following activation of signal transducer and activator of transcription 3 (STAT3) activation." (PMID 34359636, 2021). "Importantly, silencing of Cullin1 diminished K48-linked polyubiquitination of RB1, facilitating its accumulation in the context of serum starvation in MCF7 breast cancer cells." (PMID 34508104, 2021). "Also, the sensitivity of breast cancer cells to CDK7 inhibitors appears to be associated with the loss of ER and Rb1 CN expression." (PMID 34123801, 2021). "At the individual gene level and compared to controls, ATF3-induced mammary tumors exhibited reduced expression of Rb1, Esr1, and Pgr, and increased expression of Erbb2, Egfr, and the genes encoding keratins 5, 6, and 17, which is similar to basal-like human breast cancer tumors." (PMID 33652981, 2021). "Furthermore, more varieties of cancers (bladder, ovarian, uterine, liver, cervical, esophageal, breast cancers, sarcoma, diffuse large B-cell lymphoma, etc.)are estimated to carry RB1-SUCLA2 deletion with up to 5% prevalence." (PMID 34359636, 2021). "The strategies used in this study to restore PTEN expression could be relevant to other tumor suppressors in breast cancer, such as RB1." (PMID 33750924, 2021). "The retinoblastoma RB1 expression was detectable in the majority of luminal breast cancers." (PMID 32210163, 2020). "Thus, Li and coworkers have analyzed 348 ER+ breast cancers that were treated with CDK4/6 inhibitors and identified loss-of-function mutations at the level of FAT1 and RB1 genes in association with drug resistance." (PMID 32210163, 2020). "The results showed that HIST2B, DYRK2, and RB1 might be used as predictive markers for breast cancer." (PMID 31709182, 2019).
breast cancer (continued). "Our results showed that HIST2H2BE, DYRK2, MBD2, and RB1 could be used as predictive markers for breast cancer." (PMID 31709182, 2019). "Interestingly, a small number of losses were retained, including the Rb1-associated loss on chromosome 14, further supporting Rb1 as a collaborating driver in MYC-driven BRCA1-deficient mammary tumors." (PMID 30674894, 2019). "However, we divided breast cancer patients into AR/RB1 double-strong expression and AR/RB1 double-weak expression cohorts." (PMID 29261702, 2017). "However we did identify reoccurring mutations of RB1 associated with cnnLOH of chr13q14 and PTEN mutations with cnnLOH of chr10q23-26 in lung and breast cancer cell lines." (PMID 28883545, 2017). "RB1 status has only infrequently been applied to breast cancer prognostication." (PMID 21203526, 2010). "Inactivation of the RB1 gene in breast cancer was originally shown using a series of cell lines." (PMID 18782450, 2008). "In addition, the knockdown of RB1 in established breast cancer cell lines has recently been shown to increase sensitivity to a variety of DNA-damaging therapeutic agents." (PMID 18782450, 2008). "Whole-genome sequencing (WGS) of experimental breast cancer models and selected primary and relapsed tumor samples revealed that active APOBEC3 mutations contribute to resistance against endocrine and targeted therapies, primarily through RB1 mutations, leading to its functional impairment." (PMID 40244377, 2025). "While GATA3, ESR1, PIK3CA, FOXA1, FOXO3, and RB1 protein abundances were not significantly reduced in GATA3mut breast cancers, the expression of genes associated with MDM2 function and phosphorylation of genes associated with ERK signaling and aggressive phenotypes were impacted." (PMID 40439821, 2025). "Our CRISPR screen identified that drivers of ERα signaling remained essential for the viability of ER+ breast cancer cells irrespective of RB1 status, suggesting that ER+/RB-deficient breast cancer cells may still be dependent on ERα signaling." (PMID 37502925, 2023). "As we can see from the shape of the curves, decreased RB1 might be associated with poor OS in breast cancer, but the p value showed no significance (p > 0.05)." (PMID 34525987, 2021).
breast cancer (continued). "After a prolonged exposure to CDK4/6 inhibitor LY2835219, a significant amplification of CDK6 was found in several breast cancer cell lines, and this may account for a decreased CDK4/6 targeted phosphorylation of Rb1 and a decreased sensitivity of breast cancer cells to CDK4/6 inhibitor." (PMID 34123801, 2021). "Many RB1‐deficient breast cancer cells display reduced DNA replication in response to palbociclib, and reduced levels of phosphorylated RB1 alone do not explain the oncosuppressive effects of palbociclib, at least in liposarcoma patients where such data are available." (PMID 29669860, 2018). "In contrast, in breast cancer, LN metastasis is often observed at the early stage of patients with CCNE1 amplification and Rb1 deletion." (PMID 40565509, 2025). "By increasing the inhibitory effects of RB1 on tumor proliferation, CDK4/CDK6 inhibitors have demonstrated efficacy in cancers such as breast cancer." (PMID 39664374, 2024). "To test it, we measured the expression of RB1 and MYC in bladder, prostate and breast cancer cell lines and found that pRB1 protein levels were negatively correlated with MYC expression." (PMID 38424044, 2024). "To discover actionable vulnerabilities in this refractory breast cancer subtype, we performed a genome-wide CRISPR screen using ER+/RB1-knockout (RBKO) cells and identified protein arginine methyltransferase 5 (PRMT5) as a novel dependency in these cells." (PMID 37502925, 2023). "We systematically studied the effect of GLUT1–4 gene expression level on the prognosis of breast cancer, and explored the possible relationship between the expression of GLUT1–4 and RB1 in breast cancer tissues." (PMID 34525987, 2021). "Moreover, retinoblastoma gene 1 (RB1) might be used as a biomarker for the sensitivity of breast cancer cells to GLUT1 inhibitors, which brought us to the hypothesis that there might be a close correlation between the expression of GLUT1–4 and the expression of RB1." (PMID 34525987, 2021). "Altogether, these results demonstrate that RB1 and CDK6 play a pivotal role in determining the cellular sensitivity of breast cancer cells to CDK4/6i." (PMID 34508104, 2021).
breast cancer (continued). "In keeping with the observed reduction of RB1 protein abundance, immunostaining analysis also showed decreased RB1 signals in the presence of CDK4/6i in MCF7 and MDA-MB-231 breast cancer cells." (PMID 34508104, 2021). "The present study is the first to explore the relationship of mRNA expression between SLC2A1–4 and RB1, and to study the prognostic values of GLUT1–4 in breast cancer using data mining methods." (PMID 34525987, 2021). "Our results also established that inhibition of CK1ε protects hypo-phosphorylated RB1 from degradation and simultaneously abolishes CDK4/6i-induced CDK6 accumulation, thereby providing a potential therapeutic strategy for breast cancer patients." (PMID 34508104, 2021). "Different breast cancer cells showed diverse sensitivities to GLUT1 inhibitors, and the protein level of RB1 strongly correlated with the degree of sensitivity to GLUT1 inhibition in TNBC." (PMID 34525987, 2021). "The overall pattern of CNAs in TNBCs resembled that generally observed in breast cancers, with the most frequent CNA events occurring at the level of PARK2 (6%), RB1 (5%), PTEN (3%), and EGFR (5%)." (PMID 32210163, 2020). "In silico analyses showed that CCNE1/RB1 ratio correlated with palbociclib IC50 in different datasets of both breast and non-breast cancer cell lines, performing better than CCNE1 or RB1 taken separately." (PMID 30511015, 2018). "In addition, we identified multiple types of tumor suppressor gene (RB1 and BRCA1) mutations in both ovarian and breast cancer networks, which is consistent with findings that mutations in RB1 and BRCA1 are extremely important in the progression of ovarian and breast cancers." (PMID 28765560, 2017). "RB1 knockdown induces EMT events by lessening expression of E-cadherin as well as EMT-related factors Slug and Zeb-1 in breast cancer cells." (PMID 28716024, 2017). "RB1 has been shown to inhibit the E2F1 and E2F2 transcriptional factors; therefore, the allelic deletion of RB1 that was observed in 85% of breast cancer patients in our study is likely to lead to the activation of E2F1 and E2F2." (PMID 26799285, 2016). "These incongruous results could be explained by the different cell types used in the two studies (MEF and human breast cancer cell, respectively) or by the different methods used for manipulating phosphorylation, which might result in differences in site-specific phosphorylation of RB1." (PMID 26160835, 2015). "We observed a significant link between CtIP/RBBP8 and RB1 expression, as well as a strong relationship between CtIP/RBBP8 levels and specific breast cancer types." (PMID 24403251, 2013). "Indeed, high expression of CDKN2A (p16) gene products, indicative of functional defects in RB1, has been described as a defining feature of basal-like breast cancers, and it has been suggested that this may represent an important early event in bypassing cellular stress and replicative senescence." (PMID 21958427, 2011). "We investigated 88 paired primary human breast carcinomas and normal tissue genomic DNA samples to assess the frequency of LOH in RB1." (PMID 18782450, 2008). "Moreover, the expression of metastasis‐suppressing genes, including MTSS1, TIMP2, Rb1, and PTEN, gradually increased with increasing Arid4a expression in human breast cancer samples." (PMID 40066676, 2025).
breast cancer (continued). "The absence of a retinoblastoma (RB1) tumor suppressor in breast cancer induces OXPHOS, which plays a central role in promoting metastasis." (PMID 40070366, 2025). "This study analyzed the methylation statuses of CDKN2A/p16INK4A and RB1 genes in the tumor, non-tumor tissue, and cfDNA of breast cancer patients." (PMID 38716944, 2024). "Furthermore, we identified additional breast cancer genes deleted more frequently in warm/hot tumors than in cold tumors (BAP1, PBRM1, NOTCH1, CCND1, RB1)." (PMID 38714665, 2024). "Methylation panel of RB1 gene in the tumor, non-tumor tissue, and cell-free DNA of breast cancer patients." (PMID 38716944, 2024). "We used shRNA to silence expression of RB1 in HCC1428 and ZR-75-1 ER+ breast cancer cells." (PMID 38480701, 2024). "Additionally, a total of 16 gene records were retrieved for breast cancer, which includes but is not limited to BRCA1, RB1, APC and PTEN." (PMID 37195695, 2023). "Furthermore, we show that CDK4/6i treatment can alter the protein levels of RB1 and CDK6 to confer breast cancer cells with acquisition of CDK4/6i resistance." (PMID 34508104, 2021). "Interestingly, MIR3613 locus (13q14.2) located near tumor suppressor genes RB1 (13q14.2) and BRCA2 (13q13.1) on chromosome 13 and copy number of this gene segment in breast cancer was frequently altered." (PMID 33494814, 2021). "UALCAN cancer database analysis indicated that the expression of cdk4 and e2f1 in breast cancer was significantly higher than that in normal tissues (p < 0.01), while the expression of cdk6 and rb1 was not higher than that in normal tissues." (PMID 32357912, 2020). "Moreover, prior studies in pancreatic cancer, lung cancer, breast cancer, and CRC demonstrate that miR‐192 regulates expression of SERPINE1, RB‐1, BMP‐6, and DHFR and functions as a tumor suppressor." (PMID 33037736, 2020). "Our method identified not only many known cancer genes such as CCND1, MYC, ERBB2, RB1 and BRCA1 in breast cancer but also many novel protein‐coding genes as well as non‐coding RNAs that may contribute to carcinogenesis." (PMID 28719033, 2017). "In some instances, insertions were informative of deletions; for example, a reference LINE-1 in the retinoblastoma 1 (RB1) locus was only absent in the MB468 breast cancer cell line, consistent with the homozygous deletion of RB1 reported for this cell line." (PMID 27807467, 2016).